HLA-E (major histocompatibility complex, class I, E)
Diseases named in the same sentence as HLA-E in open-access papers (continued):
Sharing a sentence is not in itself a finding about the gene and the disease.
neuroblastoma (9 papers, 2013 to 2026). Neuroblastoma (NB) is the most common solid, extracranial childhood tumor. "HLA-E is a stress-induced molecule, and its expression is significantly associated with high-risk neuroblastoma (Stage 4 and MYCN amplified cases)." (PMID 33968044, 2021). "To investigate a possible involvement of HLA-E in the anti-tumor immune response against high-risk neuroblastoma, we first examined survival of the patients based on HLA-E expression." (PMID 33968044, 2021). "High HLA-E expression was significantly associated with longer survival of high-risk neuroblastoma, suggesting HLA-E is a target of the effector cells." (PMID 33968044, 2021). "The results also suggest that the HLA-E reactive CD4 CTL effector cells are functionally compromised in the TME of high-risk neuroblastoma." (PMID 33968044, 2021). "Our observation that almost all the high-risk neuroblastomas examined highly expressed both HLA-E and CADM1 lends support for this hypothesis." (PMID 33968044, 2021). "We also found that all high-risk neuroblastoma examined expressed HLA-E." (PMID 33968044, 2021). "Furthermore, we were particularly interested in the expression of HLA-E, which was expressed on high-risk neuroblastoma." (PMID 33968044, 2021). "Among nonclassical HLA class I genes, the transcriptional levels of HLA-E and -F genes were below the levels of Br and Ts in a majority of PDXs, and were particularly low or negligible in neuroblastoma, and all but one (GR-RMS-14) rhabdomyosarcoma PDXs." (PMID 38318504, 2023). "CD4 CTLs express not only the activating receptors NKG2C/E, but also the inhibitory receptor NKG2A, and these activating and inhibitory receptors NKG2C/E/A share the same ligand HLA-E expressed on neuroblastoma cells." (PMID 33968044, 2021). "On the other hand, we propose that in the absence of CD8+ T-mediated immunity, CD4 CTLs can target the HLA-E+ high-risk neuroblastoma cells in a TCR- and HLA-independent manner, which in turn would be unaffected by the PD-L1 expression status on the neuroblastoma cells." (PMID 33968044, 2021). "In contrast, high-risk neuroblastomas express the stress-responsive non-classical Class I, HLA-E molecule." (PMID 33968044, 2021). "However, the role of HLA-E in neuroblastoma (NB) migration and invasion is unknown." (PMID 27322426, 2016). "In this study, we have found that the majority of high-risk neuroblastoma expresses both HLA-E and genes responsible for GD2, but ~5% of the tumors were HLA-E+ and likely GD2 negative." (PMID 33968044, 2021). "The role of nonclassical HLA-class Ib molecules HLA-G and HLA-E in the progression of Neuroblastoma (NB), the most common pediatric extracranial solid tumor, has been characterized in the last years." (PMID 27610393, 2016).
acute myeloid leukemia (8 papers, 2016 to 2026). Acute myeloid leukemia (AML) is a group of neoplasms arising from precursor cells committed to the myeloid cell-line differentiation. "In a previously published study, we showed that HLA-E is highly expressed in acute myeloid leukemia (AML) and B-cell acute lymphocytic leukemia (B-ALL) cell lines." (PMID 38003255, 2023). "Acute myeloid leukemia (AML) cells treated with IFN-γ showed increased HLA-E surface expression, which impaired CD94/NKG2A-dependent NK cell-mediated cytolysis." (PMID 36829496, 2023). "In acute myeloid leukemia (AML), HLA-E expression is downregulated in patients compared to healthy donors." (PMID 36742337, 2023). "This was in line with the impaired CD94/NKG2A-dependent NK cell-mediated cytolysis of interferon (IFN)-γ-treated acute myeloid leukemia (AML) cells by NK cells due to the IFN-γ-mediated upregulation of HLA-E on the cell surface." (PMID 27589686, 2016). "Up-regulation of HLA-E was found in some hematologic neoplasms such as chronic lymphocytic leukemia (CLL) and acute myeloid leukemia (AML), indicating a novel strategy to restore cytotoxic ability of NK cell via blocking NKG2A on cell surface." (PMID 38396050, 2024).
colon carcinoma (8 papers, 2016 to 2024). "Moreover, a previous study showed that the cellular cytotoxicity mediated by Cetuximab, an anti-epidermal growth factor receptor monoclonal antibody, could be inhibited by HLA-E membrane expression in colon cancer cells." (PMID 32066399, 2020).
non-small cell lung carcinoma (8 papers, 2016 to 2025). A group of at least three distinct histological types of lung cancer, including non-small cell squamous cell carcinoma, adenocarcinoma, and large cell carcinoma. "In cancers, HLA-E is frequently overexpressed, such as in non-small cell lung carcinoma, breast, renal carcinoma, and gynecological cancers, and high HLA-E expression is associated with worse prognosis." (PMID 38893156, 2024). "Elevated levels of HLA-E are present in various solid cancer types such as breast cancer, gynecologic cancers, liver cancer, non-small cell lung cancer (NSCLC), pancreas cancer, and colorectal cancer." (PMID 39766165, 2024). "Expression of HLA-E is correlated with reduced immunogenicity in renal cell carcinoma, and in non-small cell lung carcinoma HLA-E expression is suggested to restrain the positive prognostic effect of infiltrating cytotoxic T cells." (PMID 32560316, 2020). "In fact, combined PD-1/PD-L1 and NKG2A/HLA-E immunotherapy has demonstrated an improved objective response in a Phase 2 clinical trial of patients with nonresectable, stage III non-small-cell lung cancer." (PMID 39857739, 2025).
HIV-1 infection (7 papers, 2008 to 2025). The type species of lentivirus and the etiologic agent of acquired immunodeficiency syndrome (AIDS). "HLA-E allelic forms influenced the course of HIV-1 infection, whereby HLA-E*01:03 was associated with 4-fold decreased risk of HIV-1 acquisition in Zimbabwean women." (PMID 30172717, 2018). "It remains unclear how the presence of this polymorphism and changes in the HLA-E ligandome during infection and inflammation affect NK cell phenotypic and functional diversity in heterogenous populations with HIV-1 infection and high levels of HCMV co-infection." (PMID 32132995, 2020). "In HIV-1 infection, HLA-E functions as a key immunoregulatory ligand by presenting peptides to HLA-E–restricted CD8+ T cells and engaging the inhibitory receptor NKG2A/CD94 on NK cells." (PMID 41440003, 2025). "To date, few human HLA-E-binding peptides derived from HIV-1 have been reported and the role of HLA-E in regulation of HIV-1 infection remains understudied." (PMID 33202884, 2020). "By inference, HLA-E likely plays an important role in balancing the immune responses to HIV-1 infection." (PMID 30172717, 2018). "The role of HLA-E in regulation of HIV-1 infection remains understudied and the knowledge ‘scattered’." (PMID 30172717, 2018). "In an effort to help start understanding the possible functions of HLA-E in HIV-1 infection, we determined novel HLA-E binding peptides derived from HIV-1 Gag, Pol and Vif proteins." (PMID 30172717, 2018). "Our search for PM9-specific HLA-E-restricted CD8+ T-cell responses in natural HIV-1 infection identified one possible responder out of 32 patients with a barely detectable response." (PMID 30172717, 2018). "In line with results previously reported with HIV-1 infection in vitro, endogenously HIV-1 infected CD4+ T cell blasts selectively down-modulated HLA-A and –B alleles while the expression of HLA-C and HLA-E molecules was conserved." (PMID 18617991, 2008). "In summary, we posit that in addition to differences in the genetic background, chronic HIV-1 infection with frequent reactivations of HCMV affects the pool of peptides presented by HLA-E and surface levels of HLA-E providing a more diverse range of ligands for CD94/NKG2 NK cells." (PMID 32132995, 2020). "Upon HIV-1 infection or reactivation in vitro, HLA-E surface levels remain unchanged or increase." (PMID 29184550, 2017). "In line with a role of HLA-E in HIV-1 infection, a genetic study in a cohort of Zimbabwean women demonstrated a four-fold reduced risk of HIV-1 acquisition in individuals homozygous for HLA-E*01:03 (HLA-EG) alleles compared to heterozygous or HLA-E*01:01 homozygous individuals." (PMID 29184550, 2017). "Thus, HIV-1 infection was shown to increase expression of HLA-E and impair NK lysis." (PMID 30172717, 2018). "Thus, further studies of HLA-E role(s) in response to HIV-1 infection are warranted." (PMID 30172717, 2018). "Studies on cytomegalovirus-vectored vaccines have shown that HLA-E-restricted CD8 T cells could recognize a broad repertoire of peptides presented upon vaccination and provide protection against HIV-1 infection." (PMID 38127067, 2023). "While numerous studies have established a role for the KIR interaction with classical HLA-I in HIV-1, recent advances have increased our understanding of non-classical HLA-E, -F, and -G in HIV-1 infection." (PMID 29184550, 2017). "Here, we inform the studies of HLA-E presentation in HIV-1 infection by identification of 4 definite and 5 candidate novel HIV-1-derived minimal peptides capable of binding to HLA-E*01:03 and discuss these results in the context of HLA-E-targeted vaccine and immunotherapeutic modalities." (PMID 30172717, 2018). "Taken together, in humans, the role of activating NKG2C:CD94 receptors in HIV-1 infection, either for increased recognition of HIV-1–infected target cells via HLA-E (independent of CMV) or for a potential HIV-1 specific NK-cell response remains to be further investigated." (PMID 29184550, 2017).
tuberculosis (7 papers, 2017 to 2025). A chronic, recurrent infection caused by the bacterium Mycobacterium tuberculosis. "Here, we describe a TCR-based bispecific molecule that potently and selectively binds HLA-E in complex with a peptide encoded by the inhA gene of Mycobacterium tuberculosis (Mtb), the causative agent of tuberculosis in humans." (PMID 38691588, 2024). "HLA-E-restricted CD8+ T cells specific for M. tuberculosis-derived peptides are detectable in the peripheral blood of individuals with either active tuberculosis or latent M. tuberculosis infection." (PMID 41440003, 2025). "Emerging evidence indicates that HLA‐E is also involved in T‐cell pathogen surveillance, with HLA‐E‐restricted peptides derived from HIV, HBV and tuberculosis implicated as ligands for protective T‐cell‐mediated immunity." (PMID 33624424, 2021). "Strong protection against tuberculosis was also observed following vaccination with RhCMV vectors, but HLA-E restricted T-cells were shown to be redundant in this system." (PMID 31040086, 2019). "Interestingly, HLA-E/NKG2C receptor expression is significantly higher in patients who have completed their treatment than in donors undergoing active anti-tuberculosis therapy." (PMID 41440003, 2025). "Recently, we have demonstrated that M. tuberculosis–specific and HLA-E–restricted CD8+ T cells are abundant but exhausted in peripheral blood of TB–HIV-1–coinfected patients, and this dysfunctional phenotype is correlated with high levels of PD-1 molecule expression." (PMID 33013888, 2020). "The presence of HLA-E/Mtb-specific T cells in people with active tuberculosis (aTB) and tuberculous infection (TBI) emphasizes the possibility of using HLA-E as a target for TB vaccination." (PMID 41440003, 2025). "HLA-E has been identified to present numerous Mtb peptides to CD8+ T cells, with multiple HLA-E-restricted cytotoxic T lymphocyte (CTL) and regulatory T cell lines isolated from patients with active and latent tuberculosis (TB)." (PMID 28475642, 2017).
co-infection (6 papers, 2010 to 2025). "We show that HIV co-infection is the main driver in changing the memory distribution of HLA-E/Mtb specific CD4+ and CD8+ T cell subsets." (PMID 39790998, 2024). "In addition to its limited genetic polymorphism, HLA-E offers another potential advantage in relation to vaccination in the context of HIV, a highly prevalent co-infection in TB." (PMID 20195504, 2010). "Thus, while HIV might affect antigen presenting cells of the myeloid lineage like monocytes and macrophages and inhibit antigen presentation by class Ia molecules, HLA-E dependent antigen presentation is likely to be less affected by HIV co-infection." (PMID 20195504, 2010). "We performed in-depth phenotyping on circulating HLA-E/Mtb specific and total T cells in individuals with various stages of TB infection and demonstrate that HIV co-infection is the main driver changing the distribution of CD4+ and CD8+ T cell memory subsets." (PMID 39790998, 2024). "This adaptation could be exploited by HLA-E-restricted CD8+ T cells, considering the high incidence of TB and HIV coinfection." (PMID 28475642, 2017). "These novel findings suggest that HLA-E/Mtb restricted CD4+ and CD8+ T cells can be induced by Mtb infection but poorly upon BCG vaccination and encouraged us to elucidate the phenotype of HLA-E restricted T cells in humans with various stages of TB, including upon HIV co-infection." (PMID 39790998, 2024). "Besides its virtual monomorphism, another advantage of targeting HLA-E by vaccination is that HLA-E is not downregulated upon HIV co-infection, in contrast to classical HLA-I molecules, which is an important benefit as infection with HIV and TB significantly overlap in endemic areas." (PMID 39460296, 2024). "HLA-E is a virtually monomorphic antigen presentation molecule and is not downregulated upon HIV co-infection." (PMID 39790998, 2024). "HLA-E restricted Mtb specific CD8+ T cells are present in the circulation of individuals with active TB (aTB) and Mtb infection (TBI) with or without HIV co-infection, making HLA-E restricted T cells interesting vaccination targets for TB." (PMID 39790998, 2024). "In addition to genetic differences between our cohort and those studied previously, the presence of chronic HIV-1 and HCMV co-infection in our study subjects may also have contributed to the lack of significant difference in surface HLA-E expression between study groups." (PMID 32132995, 2020). "TCRs can also recognize HLA-E–peptide complexes, and HLA-E-restricted CD8+ T cells have been identified in the circulation in patients with malignancies and infections in active TB (aTB) or Mtb-infected (TBI) individuals with and without HIV co-infection." (PMID 39460296, 2024).
Ewing sarcoma (6 papers, 2020 to 2024). A small round cell tumor that lacks morphologic, immunohistochemical, and electron microscopic evidence of neuroectodermal differentiation. "NKG2A-deficient NK cells had improved cytotoxic functionality in targeting HLA-E-expressing and HLA-E-deficient cancer cells deriving from Ewing’s sarcoma, osteosarcoma, and AML." (PMID 39339180, 2024). "Here, we studied the capacity of two nonclassical HLA molecules with known immunosuppressive function, HLA-G and HLA-E, to prevent antigen-specific immune effector functions of gene-engineered T cells against Ewing sarcoma." (PMID 34201079, 2021). "However, HLA-E transcript levels were slightly elevated in four out of six Ewing sarcoma, all four HGG, three out of four NRSTS, and five out of eight osteosarcoma PDXs." (PMID 38318504, 2023). "Moreover, as previously shown for HLA-G, HLA-E was detected in a high proportion of human Ewing sarcoma biopsies." (PMID 34201079, 2021). "We detected low but consistent HLA-E transcript levels in all four HGG and ~60 to 75% of Ewing sarcoma, osteosarcoma, and NRSTS PDXs." (PMID 38318504, 2023). "We conclude that blockade of HLA-G and HLA-E immune checkpoints is not a promising strategy for enhancing T cell therapies in Ewing sarcoma." (PMID 34201079, 2021). "Based on our finding that Ewing sarcomas (EwS) respond to chimeric antigen receptor (CAR) gene-modified effector cells through upregulation of human leukocyte antigen G (HLA-G), we hypothesized that nonclassical HLA molecules, HLA-G and HLA-E, contribute to immune escape of EwS." (PMID 34201079, 2021).
multiple sclerosis (6 papers, 2012 to 2025). A progressive autoimmune disorder affecting the central nervous system resulting in demyelination. "A similar function has been attributed to human neuroantigen-specific CD8+ Treg, which recognize HLA-E-bound peptides and are present in the circulation of patients with multiple sclerosis." (PMID 27965674, 2016). "In patients with multiple sclerosis (MS), increased frequencies of EBV specific, HLA-E restricted CD8+ T-cells have been found to be associated mostly with the relapsing remitting form of the disease rather than the progressive form." (PMID 27699181, 2016). "Associations between HLA‐E*01 genotype and Multiple Sclerosis diagnosis in individuals without or with a history of Infectious Mononucleosis diagnosis based on a Cox model including the interaction between HLA‐E*01 and Infectious Mononucleosis." (PMID 40192262, 2025). "Glatiramer acetate (GA) introduced in the therapy of multiple sclerosis has been shown to induce CD8+ Ts, which seem to recognize GA on the cell surface and directly kill CD4+ T cells in a HLA-E-dependent manner." (PMID 27965674, 2016).
ovarian tumor (6 papers, 2011 to 2023). "This represents a promising strategy for future clinical studies in HLA-E+ ovarian tumors." (PMID 38067396, 2023). "From a therapeutic perspective, humanized monoclonal antibodies targeting NKG2A (Monalizumab) are readily available and currently in clinical trials for cancer, hence representing a promising strategy for future clinical studies in HLA-E positive ovarian tumors." (PMID 35267497, 2022). "High expression of β2m in ovarian tumours is also associated with overexpression of HLA-E, a non-classical MHC class I molecule." (PMID 35073851, 2022).
pancreatic cancer (6 papers, 2016 to 2025). "In cancer, HLA‐E expression has been correlated with poor prognosis in patients with glioblastoma, pancreatic cancer and head and neck squamous cell carcinoma (HNSCC), among others, a fact that is indicative of the potential of the HLA‐E‐NKG2A pathway as a target for immunotherapeutic interventions." (PMID 37782273, 2023).
chronic lymphocytic leukemia (5 papers, 2020 to 2025). "HLA-E*01:01 is linked to comparatively low HLA-E surface expression, whereas substantially higher HLA-E expression is found in the presence of at least one HLA-E*01:03 allele in healthy individuals as well as in hematological disorders such as acute leukemia or chronic lymphocytic leukemia." (PMID 33218185, 2020). "CD40L and IL-4 have recently been shown to inhibit NK cell activation against chronic lymphocytic leukaemia (CLL) cells via the HLA-E:NKG2A immune checkpoint axis." (PMID 40977848, 2025). "The use of anti-NKG2A mAbs for therapeutic blockade of NKG2A restored the cytolytic activity of NK cells against HLA-E+ chronic lymphocytic leukemia (CLL) targets, thus improving NK cell dysfunction." (PMID 32714324, 2020).
head and neck cancer (5 papers, 2016 to 2024). A primary or metastatic malignant neoplasm affecting the head and neck. "The large number of human solid tumors such as colon, lung, pancreas, stomach, liver, head and neck carcinomas, in which the overexpression of NKG2A receptor and/or their ligand HLA-E has been often associated with a poor prognosis." (PMID 39229258, 2024). "In tumor cells (hematological as well as solid tumors), HLA-E is frequently overexpressed as compared to their non-transformed counterparts, such as lung, cervix and head/neck carcinoma to avoid killing." (PMID 39229258, 2024). "Moreover, the NKG2A blockade enhanced anti-tumor immunity in vivo in head and neck cancers and the response of CD8+ T cells isolated from bladder tumors to HLA-E-expressing target cells." (PMID 37444472, 2023).